EGFR (epidermal growth factor receptor)
Diseases named in the same sentence as EGFR in open-access papers (continued):
Sharing a sentence is not in itself a finding about the gene and the disease.
breast carcinoma (continued). "Notably, both EGFR and c-Src stimulated pathways can induce activation of a transcription factor STAT5, which is needed for E2-induced breast cancer cell proliferation, in some cell lines." (PMID 26258011, 2015). "In addition, PTPH1 also increases breast cancer sensitivity to another TKI gefitinib (Gef), a specific EGFR inhibitor that has also been used clinically." (PMID 26079946, 2015). "Here, we determine the role of TIMP3 through TNF in different compartments and during different stages of a breast cancer mouse model that is independent of ErbB/EGFR growth factor release." (PMID 25807548, 2015). "Different combinatorial regimes have been approached; thus, the combination of gefitinib with calcitriol or their synthetic analogs resulted in a greater antiproliferative effect than with either of the agents alone in EGFR and HER2 positive breast cancer cells." (PMID 26258011, 2015). "In addition, the importance of EGFR signaling in tumor dormancy and recurrence of FGFR1-driven mammary tumors provides a further rationale for combinatorial treatments in breast cancers harboring FGFR1 amplification." (PMID 26581390, 2015). "Interestingly, a previous study of PTPRG in breast cancer also confirmed that PTPRG regulates the ERK1/2 pathway, which is also one of the key EGFR-regulated signaling pathways." (PMID 25970784, 2015). "As the current study was performed in breast cancer cell lines, it suggests a key role for PLD2 in maintaining the levels of EGFR and could be used as a target for modulating its expression." (PMID 26493292, 2015). "For example, a recent report showed that neurotensin (NTS) and its high affinity receptor (NTSR1) enhances EGFR, HER2, and HER3 activation, but lapatinib could reduce the tumour growth of breast cancer cells overexpressing NTS and NTSR1." (PMID 25691057, 2015). "Experiment was performed to examine the effects of EGCG on vascular endothelial growth factor (VEGF) production by YCU-H891 HNSCC and MDA-MB-231 breast carcinoma cell lines and found that treatment with EGCG inhibited the constitutive activation of the EGFR, Stat3, and Akt in both cell lines." (PMID 25977926, 2015). "Under these conditions, which may be represented by SkBr2 breast cancer cells, GPER/EGFR signaling could allow stimulatory effects by environmental estrogens, as shown in the present study and in previous studies." (PMID 25616260, 2015). "In addition, in colon and breast cancer cells, FAK survival signaling exerts its roles by combining with EGFR." (PMID 25997441, 2015). "Along with cytokeratin 5/6 as a marker of basal-like breast cancers, the EGFR expression is a marker of poor prognosis regardless of the expression of ER or PR." (PMID 25955731, 2015). "Transfection of constitutively active AMPKα also leads to decreased HER2 and EGFR phosphorylation, reduced downstream signaling associated with these receptor tyrosine kinases (RTKs), and reduced breast cancer cell growth, confirming effects of AMPK activity on HER2/EGFR." (PMID 26143491, 2015). "To date, exploitation of the overexpression of HER2 is part of the management of a breast cancer patient whereas EGFR, HER3, and HER4 determinations are still exploratory and not used in clinical practice." (PMID 25887735, 2015). "Although expressed in nonmalignant cells, the EGFR is highly expressed in a variety of tumors leading to its validation as a therapeutic target in several human tumors, including colorectal cancer, breast cancer, and head and neck cancer." (PMID 25699271, 2015). "Thus, dual kinase inhibition directed against EGFR and HER2 was and still is an attractive potential approach for breast cancer therapy." (PMID 26068969, 2015). "Sukocheva and coworkers showed in MCF-7 breast cancer cells that estradiol increased SphK1 activity and the formation of S1P, with subsequent binding of S1P to one of its receptors, S1P3, which in turn transactivated EGFR." (PMID 26221601, 2015).
breast carcinoma (continued). "Given that overexpression of Rab31 in breast cancer cell lines actually enhanced proliferation, Rab31, when elevated in the presence of MUC1-C may enhance instead of retard EGFR signalling in these cells." (PMID 25472813, 2015). "Considering that NF-κB is activated by epidermal growth factor receptors (EGFR), the amplification of the EGFR gene HER2/ERBB2/neu in a significant fraction of human breast cancers may provide a partial explanation for downregulation of KLF2 in breast tumors." (PMID 26416422, 2015). "Since then, many researchers have reported differing findings on the prognostic value of EGFR in breast cancer, and there is still no agreement on the relationship between EGFR and clinical outcome." (PMID 25429827, 2015). "Accumulating reports have demonstrated that EGFRvIII, the most common EGFR mutant forms with constitutively activated kinase domain, expresses in various human cancers, including breast cancer, and it has not been detected in normal adult human tissue." (PMID 26474285, 2015). "Moreover, ER binds EGFR and this interaction is enhanced in TAM-resistant breast cancer, indicating an inhibitory activity of this protein-complex in ER therapeutic target activity." (PMID 26079946, 2015). "Although it was shown that FABP5 mRNA is expressed in TNBC patient samples and predicts worse prognosis, a detailed analysis of its protein expression and especially its correlation with EGFR has not been extensively studied in breast cancer, especially TNBC." (PMID 25779666, 2015). "The association between ANXA1 expression and basal markers (EGFR-CK5/6) as shown in this study was also described in our previous work using a smaller cohort of breast cancer patients, suggesting that ANXA1 may play a role in EGFR trafficking." (PMID 26137966, 2015). "Because of the mechanistic relationship between EGFR and HER2, EGFR measurement may provide a method for personalizing treatment in breast cancer, beyond the single assay for HER2." (PMID 25887735, 2015). "Because EGFR signaling activates ARF6 and induces breast cancer invasion, we tested whether impaired EGFR signaling could reproduce the intrahepatic biliary defects observed in arf6-ATG MO-injected larvae." (PMID 26379158, 2015). "Basal-like breast cancers are a subset of breast cancers characterised by triple negativity for ER, PR and HER2, and the expression basal/myoepithelial markers such as CK5/6, CK14 and EGFR." (PMID 26152113, 2015). "Transduction of miR-146a may down-regulate expression of epidermal growth factor receptor (EGFR), and inhibit invasion and migration of breast cancer cells." (PMID 26033453, 2015). "EGFR, PI3K, and mTORC1 inhibitors are being evaluated to treat breast cancer patients." (PMID 25051360, 2014). "Clinically, luminal breast cancers exhibiting the appropriate heterogeneity for treatment by this combination could be easily identified using ER/PR and CK5 or EGFR as biomarkers." (PMID 25116921, 2014). "We cultured ER-positive breast cancer MCF7 cells in the tumorsphere media and under suspension condition to form tumorspheres, and performed Western blot analysis to assess expression of ER-α36, EGFR and HER2 in tumorsphere and parental cells." (PMID 25203051, 2014). "Moreover, overexpression of EGFR and HER2, whose ligand (i.e. the epidermal growth factor) is capable of inducing PKD1 activity, was observed in antiestrogen-resistant breast cancers." (PMID 25287328, 2014). "In erbB2+ breast cancer tissues, preferential phosphorylation of erbB3, but not EGFR, has been observed." (PMID 24886126, 2014). "Most metastatic breast cancers show expression of either EGFR or erbB2, whereas upregulation of both is not typical." (PMID 24886126, 2014). "As we show here that KIAA1199 and EGFR/HER2/HER3 levels are positively correlated in transformed keratinocytes and in breast cancer-derived cells, KIAA1199 may be essential for the constitutive activation of EGFR signalling seen in multiple malignancies." (PMID 25366117, 2014).
breast carcinoma (continued). "Both EGFR and HER2 were also highly expressed in MCF7/ER36 cells, indicating that increased ER-α36 expression is one of the mechanisms by which ER-positive breast cancer cells gained EGFR and HER2 expression." (PMID 25203051, 2014). "Indeed, the combination of AG490 and AG1478 was more potent than the inhibitor alone in killing EGFR-overexpressing cells, i.e., A431 and MDA-MB-468 (human breast carcinoma)." (PMID 25063218, 2014). "Since EGFR overexpression is common in breast cancer, the impact of CXCL16 alteration on proliferation may be masked by EGFR overexpression or other genetic alterations." (PMID 24864132, 2014). "The basal-like breast cancer is IHC characterized by overexpression of cytokeratin 5/6/14 and epidermal growth factor receptor and lack of expression of ER, PR and HER2." (PMID 24731479, 2014). "ErbB3 may be considered as a valuable biomarker to predict the efficacy of EGFR- and/or erbB2-targeted therapy in the treatment of NSCLC and erbB2+ breast cancer, respectively." (PMID 24886126, 2014). "Their studies showed that activation of EGFR and HGF might contribute to drug resistance of breast cancer through the downregulation of phosphosites such as Thr654 and Thr669 of EGFR." (PMID 25478227, 2014). "Inhibition of HER RTKs by HER pan-inhibitor CI-1033 notably enhances the radiosensitivity of human colon carcinoma cells both in vitro and in vivo, while HER1 inhibition by gefitinib and HER2 inhibition by herceptin, respectively, radiosensitizes EGFR amplified glioma cells and breast cancer cells." (PMID 25174607, 2014). "The simultaneous detection of both EGFR and EMT markers in CTCs may improve prognostic or predictive information in patients with operable breast cancer." (PMID 25277187, 2014). "The essential role of KIAA1199 in EGFR signalling is not restricted to cervical cancer cells as similar observations were also made in all breast cancer cell lines tested so far." (PMID 25366117, 2014). "Nevertheless, whether NILCO and targets are differentially-expressed in human breast cancer tissues, in relation to ER, PR and HER2 as well as EGFR and AR statuses, is unknown." (PMID 24716804, 2014). "Validated cancer drivers such as ERRBB2, EGFR, and KRAS demonstrated high copy number versus mRNA expression correlation in the corresponding cancer types they regulate (ERBB2 r = 0.9 in breast cancer, EGFR r = 0.8 in lung adenocarcinoma, KRAS r = 0.9 in ovarian cancer)." (PMID 24874471, 2014). "In this study, we unexpectedly found that HDAC inhibitor trichostatin A (TSA), but not suberoylanilide hydroxamic acid (SAHA), represses EGFR protein level independently of HDAC inhibition in the lapatinib-treated breast cancer cells." (PMID 24707474, 2014). "Accordingly, GPER-mediated CAF-dependent estrogenic effects on the tumor-associated stroma are conceivable, and CAF is likely to contribute to breast cancer progression, especially TAM resistance, via a positive feedback loop involving GPER/EGFR/ERK signaling and E2 production." (PMID 24481325, 2014). "Additional pathways included regulation of eNOS pathway enriched for breast cancer, transcriptional role of AP1 for endometrial cancer, activin A signal regulation, and development of beta-adrenergic receptor transactivation of EGFR enriched for ovarian cancer." (PMID 25171249, 2014). "Identification of HER2/neu led to the development of trastuzumab (Herceptin), a humanized monoclonalantibody of the IgG1 type directed against the extracellular portion of human EGFR HER2/neu, and revolutionizedthe management of both early and advanced breast cancer." (PMID 26110069, 2014).
breast carcinoma (continued). "Previous study has shown that AZD8931 inhibits human tumor xenograft growth with different sensitivities to agents targeting either EGFR or HER2 in a variety of models including one human breast cancer cell line BT-474, which expresses ER/PgR, high levels of HER2, and moderate levels of EGFR." (PMID 24886365, 2014). "The objective of this study was to detect EMT phenotype through Vimentin (VIM) and Slug expression in cytokeratin (CK)-negative CTCs in non-metastatic breast cancer patients and to determine the importance of EGFR in the EMT phenomenon." (PMID 25277187, 2014). "Furthermore, leptin transactivated and induced the expression of ER, EGFR, HER2 and IGF-1R in breast cancer." (PMID 24716804, 2014). "Even though EGFR is not a strong oncogene in breast cancer and the overexpression of EGFR cannot induce mouse mammary cancer by itself, it can co-operate with ErbB2 in MCF10A cells making them invasive in 3-dimensional Matrigel assays." (PMID 24709902, 2014). "Such pathways include the Epidermal Growth Factor Receptor (EGFR) Tyrosine Kinase (HER or HER) and Notch pathways, which have been found to communicate with one another to overcome treatment as well as promote Breast Cancer Stem Cell (BCSC) cell fate." (PMID 25566499, 2014). "TAM, in addition to E2 and the GPER agonist G1, promoted proliferation, cell-cycle progression, and E2 production via the GPER/EGFR/ERK axis in breast CAFs, providing novel insights into the GPER-mediated CAF-dependent mechanism of TAM resistance in breast cancer." (PMID 24481325, 2014). "Since PKCζ has been reported to be a mitogenic downstream mediator of EGFR in cell signal transduction, inhibiting PKCζ could target HER2 or EGFR and potentially enhance breast cancer chemotherapy." (PMID 24603690, 2014). "Microarray analysis of tissue obtained from breast cancer patients shows that elevations in Met expression occur in a significant percentage of EGFR/HER2 negative tumors." (PMID 26932375, 2014). "Here, we hypothesized that tamoxifen activates crosstalk between the GPR30 and the EGFR signaling pathway, while suppressing ER activation in GPR30/ER + breast cancer patients." (PMID 24289103, 2013). "In addition, these authors demonstrated that PAR1-stimulated EGFR and ErbB-2 transactivation sustains p42/p44 MAPK signalling and promotes breast carcinoma cell invasion." (PMID 24215724, 2013). "As expected, EGFR inhibition resulted in reduced expression of EXO1 in MDA-MB-468, thereby illustrating the involvement of EGFR/RAS cascade in the regulation of EXO1 gene expression in breast cancer cells." (PMID 24147022, 2013). "Overexpression of the epidermal growth factor (EGFR) family of proteins has been demonstrated to have significant negative therapeutic significance for breast cancer." (PMID 23816254, 2013). "As enhanced interaction between GPR30 and EGFR signaling was seen to increase Erk1/2 phosphorylation in TAM-R cells, and Erk1/2 activates gene transcription leading to breast cancer proliferation, we investigated the role of GPR30/EGFR crosstalk in cell survival." (PMID 24289103, 2013). "The PET radiotracer, 11C Iressa, has been reported in clinical trial for EGFR imaging in lung cancer, but no application in breast cancer imaging has been published." (PMID 23533377, 2013). "EGFR/HER1 and HER2 may play important roles, and these receptors have been found upregulated in response to endocrine treatment in ER positive breast cancer cell lines." (PMID 23991224, 2013). "It was also reported that sensitivity of breast cancer cells to SFN is connected with upregulation of p38 MAP kinase and caspase -7 activation in MCF-7 cells, global changes in gene expression or downregulation of ER, EGFR or HER2 mRNAs." (PMID 23389114, 2013). "Clinical testing of EGFR TKIs in breast cancer patients demonstrated that EGFR TKIs are not effective in treating TNBC even though EGFR is overexpressed." (PMID 23593472, 2013).
breast carcinoma (continued). "Metaplastic breast carcinomas are negative for Her-2 but frequently express EGFR (Her-1): potential relevance to adjuvant treatment with EGFR tyrosine kinase inhibitors?" (PMID 23734272, 2013). "In breast cancers that are not responsive to EGFR inhibitor therapy, not only Src but also Met, the hepatocyte growth factor (HGF) receptor that is itself a tyrosine kinase, is implicated in cancer cell malignancy." (PMID 23702846, 2013). "This could be explained at least partially by low expression of EGFR and also HER2 which can dictate gefitinib’s activity in breast cancer cells." (PMID 24146879, 2013). "This study suggests that erlotinib is worthy of further investigation in ER+ breast cancers and not Her2 positive or triple negative breast cancers and EGFR positivity does not necessarily predict response." (PMID 23741308, 2013). "Similar to EGFR, disrupting VEGFR signaling pathways has been commonly used as molecular target therapy for highly vascularised tumors, such as colorectal and hepatic cancer, lung cancer, and breast cancer." (PMID 23434665, 2013). "In this study, we aimed to investigate whether co-inhibition of EGFR and IGF-1R enhances the radiosensitivity of breast cancer cells with different expression of the two receptors, and also to assess the potential molecular mechanisms." (PMID 23777562, 2013). "SOX2 plus EGFR had similar prognostic impact on ER-negative but not specific subtypes of breast cancer (data not shown)." (PMID 23982413, 2013). "Metaplastic breast carcinomas are consistently negative for ER, PgR and Her-2/neu but positive for EGFR, as in nearly all of our cases." (PMID 24083491, 2013). "In fact, a breast cancer study has indicated that EGFRvIII expression is not a consequence of EGFR locus rearrangement or amplification but is rather due to alterative splicing events." (PMID 23806066, 2013). "Moreover, western blot analysis indicates that miR-1258 inhibits phosphorylation and expression of heparanase-related proteins AKT, EGFR, MMP-9, and COX-2, resulting in decrease of breast cancer brain metastasis." (PMID 23984412, 2013). "Subsequent studies using breast cancer and other types of human cancer cells demonstrated that the signal transducer and activator of transcription protein (STAT) is a possible mediator of the Y845 phosphorylation-dependent synergism of EGFR and Src." (PMID 23702846, 2013). "For molecular imaging strategies, a putative panel consisting of markers for EGFR, IGF1-R, FGFR2, GLUT1, CAXII, CD44v6 was positive in 77% of cases and might be considered for development of molecular tracers for male breast cancer." (PMID 23308200, 2013). "Likewise, activation of PAR1 by thrombin induces persistent EGFR and ErbB-2 transactivation, sustained p42/p44 MAPK signalling, and invasion in breast cancer cells." (PMID 24215724, 2013). "Since HNSCC share common attributes with human breast cancer cells (i.e., expression of EGFR, estrogen receptor (ER)), it is not unreasonable to draw from studies using human breast cancer cells (MCF-7)." (PMID 24970177, 2013). "The ability of curcumin to downregulate EGFR and HER-2 oncoproteins and affect the PI3K/Akt and MAPK pathways, with which herceptin interfered, raised interest in the potential utility of curcumin in the treatment of HER-2-positive breast cancer." (PMID 21876713, 2012). "In the clinic, breast cancers do not respond to EGFR TKIs; however, a number of EGFR-expressing TNBC cell lines show sensitivity to EGFR TKIs." (PMID 22788954, 2012).